IL7 (interleukin 7)
Diseases named in the same sentence as IL7 in open-access papers (continued):
Sharing a sentence is not in itself a finding about the gene and the disease.
COVID-19 (continued). "Studies in patients with sepsis and COVID-19 have shown that IL-7 did not increase circulating levels of the pro-inflammatory cytokines IL-6 or TNF-α compared to patients who received placebo." (PMID 41550947, 2025). "Similarly, regarding inflammatory cytokines, high levels of several cytokines, such as IL-1β, IL-2, IL-6, IL-7, IL-8, IL-10, CXCL10/IP-10, MCP-1, and TNF-α have already been described according to the severity of COVID-19." (PMID 39861879, 2025). "The mean IL-7 and IL-15 levels were also only marginally elevated in the vaccinees irrespective of the COVID-19 exposure before or after the vaccination." (PMID 41012170, 2025). "Compared with those in healthy individuals, the levels of IFN-γ, IL-12 (p70), IL-13, IL-1β, IL-2, IL-4, IL-5, IL-6, GM-CSF, IL-17A, IL-27, IFN-α, IL-15, IL-1RA, IL-7, eotaxin, GRO-α, IP-10, MCP-1, MIP-1α, MIP-1β, SDF-1α, and RANTES in mild COVID-19 patients were significantly greater." (PMID 39351097, 2024). "Among patients enrolled within 7 days of symptom onset, evidence of pro-inflammatory monocyte/macrophage (IL-1Ra, IL-1β, IL-6, CXCL10), NK cell (IL-15), Th1/Th17-pathway (IL-7, IL-15, IL-17F), and endothelial (VEGF-A) activation were apparent in patients with severe COVID-19." (PMID 38368384, 2024). "Moreover, the expression of proinflammatory cytokines such as IL-1RA, IFN-α, IL-7, IP-10, MIP-1α, and MIP-1β is strongly correlated with the severity of COVID-19." (PMID 39351097, 2024). "Plasma levels of IL-2, IL-7, IL-10, granulocyte colony-stimulating factor (G-CSF), IP-10, MCP1, macrophage inflammatory protein 1α (MIP1α), and tumor necrosis factor (TNF) have been observed in patients with severe COVID-19 were higher than in healthy adults." (PMID 38648205, 2024). "As expected, performing TPE decreased the amount of anti-type I IFN auto-antibodies and improved the elimination or limited the production of certain inflammatory mediators (IL-18, IL-7, CCL2, CCL3, etc.)circulating in the blood of COVID-19 patients, compared to ST controls." (PMID 39896810, 2024). "Examples of potential mHLA-DR-directed interventions that could find utility in AP and COVID-19 include several immunostimulatory agents, including IFN-γ, recombinant IL-7, and granulocyte-macrophage colony-stimulating factor." (PMID 36834656, 2023). "Serum IL-7, a member of IL-2 family was also compared in patients with both severe and nonsevere COVID-19." (PMID 37649897, 2023). "Plasma levels of IL-2, IL-7, IL-10, granulocytic stimulator, IP-10, human monocyte chemotactic protein 1, and human macrophage inflammatory protein 1α in ICU patients with COVID-19 are higher than those in mild patients, indicating strong correlation between cytokine storm and disease severity." (PMID 38156008, 2023). "Overproduction of cytokines, including IL-17, IL-7, IL-1β, IL-9, IL-2, IL-10, TNF-α, GM-CSF, G-CSF, IFN-γ, MCP1, MIP1A, MIP1B, CXCL10 and CXCL8, by monocytes and macrophages has been reported in severe COVID-19 cases." (PMID 36793739, 2023). "Elevated levels of cytokines such as IL1B, IL7, IL8, IL9, and IL10, monocyte chemoattractant protein and tumor necrosis factor (TNF), among others, in COVID-19 have been reported and elevated proinflammatory cytokine levels have been found to correlate with disease severity." (PMID 35172279, 2022). "Single-cell transcriptome analyzes of human inflammatory monocytes from COVID-19 and RA patients showed that a group of CD127 (IL-7 receptor subunit) positive cells induced initially inactive monocytes to respond to IL-7 and negatively affected the inflammatory phenotype of monocytes." (PMID 35464423, 2022). "Non-pregnant patients with severe COVID-19 have been found to have greater levels of IL-2, IL-6, IL-7, IL-10, IP-10, MCP-1, TNF-α, macrophage inflammatory protein 1 alpha, and granulocyte-CSF than those with mild and moderate infections." (PMID 36383608, 2022).
COVID-19 (continued). "Indeed, IL-7 and the CXCR3 ligands are part of the protein network that is maintained in the post-COVID-19 airway." (PMID 35151371, 2022). "TNF-, IL-2, IL-6, IL1B, IL7, IL10, IFN-, GCSF, CXCL10, CCL2, ferritin, D-dimer, fibrinogen, leukocytosis, and C-reactive protein (CRP) levels are significantly higher in critically ill COVID-19 patients." (PMID 35645351, 2022). "Analyzing the mortality, IL-7 is increased in non-survivor COVID-19 patients with low eGFR, with a trend to be increased in non-survivors compared to survivor patients independently by renal function." (PMID 36287942, 2022). "Regarding the interleukins, gene expression of IL6, but not IL7, was increased in PBCs of COVID-19 patients (by 89%) as compared to control subjects (Student’s t test)." (PMID 36009555, 2022). "Circulating IL-7 is essential for lymphocyte proliferation and terminal differentiation, and its levels were shown to be higher in patients with severe COVID-19 than those with non-severe COVID-19." (PMID 35625671, 2022). "IL-7 can be safely administered to critically ill COVID-19 patients without exacerbating inflammation or pulmonary injury." (PMID 36286038, 2022). "In addition, it was also found that the plasma levels of IL2, IL7, IL10, IL-6, TNFα, and e lymphopenia were higher in patients with COVID-19." (PMID 35295802, 2022). "Higher blood levels of inflammatory biomarkers (e.g. CRP) and cytokines (e.g. IL2, IL7, IL10, etc.)have been reported in COVID-19 patients admitted to the ICU3, and IL6 and IL10 have been determined to be strong discriminators for severe disease and death, consistent with our findings." (PMID 33627696, 2021). "In an examination of case series, critically ill COVID-19 patients who were treated with IL-7 showed increased lymphocyte count without any evidence of hyperinflammation and lung damage." (PMID 34603318, 2021). "A study conducted in ICU and non-ICU COVID-19 patients in Wuhan, China, reported elevated levels of IL-1β, IL-7, IL-8, IL-9, IL-10, FGF, G-CSF, GM-CSF, IFN-γ, IP-10, MCP-1, MIP-1α, MIP-1β, PDGF, TNF-α and VEGF in patients compared to healthy controls." (PMID 34603318, 2021). "The cytokine storm landscape of COVID-19 patients was further demonstrated in a retrospective study showing higher concentrations of IL-2, IL-7, IL-10, G-CSF, C-X-C motif chemokine ligand (CXCL)-10, C-C motif chemokine ligand (CCL)-2, CCL-3, and TNF-α in the plasma of severe COVID-19 patients." (PMID 33584335, 2020). "However, studies that seek to evaluate the expression profile of IL-7 and CD127 in COVID-19 patients need to be carried out." (PMID 33193331, 2020). "The effect of compassionate use of IL-7 in 12 critically ill patients with COVID-19 and severe lymphopenia was compared to the outcome of 13 matched controls who did not benefited from IL-7." (PMID 33335532, 2020). "The findings of this study suggest that IL-7 can be safely administered to critically ill patients with COVID-19 without exacerbating inflammation or pulmonary injury." (PMID 32697322, 2020). "Principle behind use: severe cases of COVID-19 are characterized by a cytokine storm defined as a sudden production of cytokines, such as IL-2, IL-7, IL-10, granulocyte colony-stimulating factor (G-CSF), MCP1, MIP-1a, and TNF-α, secondary to the upregulation of the inflammatory process in COVID-19." (PMID 32953365, 2020). "Increased levels of interleukins (IL-1 α, IL-7, IL-17, and IL-18) and chemokines (CCL11, and CXCL1) were found only in the COVID-19-only, whilst PLWH/COVID-19, had increased levels of four different interleukins (IL-5, IL-6, IL-9, and IL-15) and one chemokine (CXCL10) compared to COVID-19-only." (PMID 41516165, 2025). "Recently, IL-7 has been used clinically in multiple myeloma patients receiving CAR-T cell therapy, in patients with urothelial cancer who are receiving checkpoint inhibitors, in patients undergoing endogenous lymphocyte cell therapy, and in critically-ill lymphopenic patients with COVID-19." (PMID 41550947, 2025).
COVID-19 (continued). "In contrast to COVID-19, which showed markedly elevated plasma concentrations of 11 SMs, we observed decreased levels of several SMs, mainly pro-inflammatory cytokines (e.g., IFN-γ, IFN-α2, TNF-α, IL-7, IL-17A, and IL-15) in both the remission and acute phases of TTP." (PMID 39337495, 2024). "Accordingly, these results suggest that appropriate administration of IL-7 with or without other agents could be applied to critically ill COVID-19 patients with severe lymphopenia." (PMID 36793739, 2023). "Importantly, we also showed for the first time that persistent changes in Tie-2, Flt-1, bFGF, IL-7, and TNFα were uniquely seen in patients following recovery following COVID-19, but not in patients recovering from severe sepsis." (PMID 36844209, 2023). "Current clinical studies have shown that the expression levels of inflammatory factors (IL-2, IL-7, IFN-γ, and TNF-α) positively correlate with the severity of COVID-19, suggesting that PLA2G4A may be a key target in the development of COVID-19." (PMID 36210820, 2022). "The expression may be important in treatment with pharmacological IL-7, a potential drug for severe disease that has been successful in restoring lymphocyte count and function in patients with non-severe COVID-19." (PMID 35625671, 2022). "Alternatively, identifying upstream regulators of the inflammatory pathway, as for example IL-17 studied in mice 48, or regulators of lymphopoiesis, as for example IL-7 and thymic stromal lymphopoietin (TSLP), may be needed to understand COVID-19 cytokine pathogenesis." (PMID 36313221, 2022). "However, for the lack of strong evidence to support the use of IL-7 in COVID-19 patients, more studies are needed to approve its clinical use." (PMID 36558048, 2022). "A significant increasing trend of IL-1β, IL-1ra, IL-2, IL-4, IL-5, IL-6, IL-7, IL-8, IL-10, IL-12(p70), IL-15, IL-17, FGF-b, G-CSF, GM-CSF, IFN-γ, IP-10, MCP-1, MIP-1α, PDGF, TNF-α, and VEGF was observed in the three groups (Controls ≤ Mild COVID-19 ≤ Severe COVID-19)." (PMID 34675240, 2021). "Additionally, in non-severe COVID-19—although significantly lower than severe ones—blood-cytokine levels (for example IL-1β, IL-1RA, IL-2R, IL-6, IL-7, IL-8, IL-9, IL-10, IFN-γ, TNF-α, G-CSF, GM-CSF, IP10, MCP1), can be increased." (PMID 34572585, 2021). "IL-7 treatment did not significantly increase the frequency of MAIT cells expressing TNF-α or granzyme B in COVID-19 patients, but it successfully increased both the perforin expression level (MFI) (p = 0.001) and the frequency of MAIT cells expressing perforin (p = 0.001)." (PMID 34238985, 2021). "Another study showed a similar trend, with plasma concentrations of IL-2, IL-7, IL-17, IL-10, MCP-1, MIP-1A, IP10, and TNF-α being observed to be higher in COVID-19 patients undergoing treatment in intensive care units than in any other category of COVID-19 patients." (PMID 32984253, 2020). "In addition, SARS-CoV-2-specific T cells from the peripheral blood of convalescent individuals of COVID-19 show high expressions of CD127, a receptor necessary for homeostatic cell proliferation triggered by IL-7, which may be related to the recovery observed." (PMID 33193331, 2020). "Signaling by CD127/IL-7 is involved in numerous key aspects of T-cell survival and proliferation, therefore, increased CD127 expression levels on T cells could be involved in overcoming lymphopenia in patients with COVID-19 and thus lead to a decrease in lung inflammation." (PMID 37034572, 2023). "The elevation of IL-7, granulocyte-macrophage colony stimulating factor, interferon-gamma (IFN-γ), and fibroblast growth factor in COVID-19 patients might be involved in the development of AKI in COVID-19 patients and induced endothelial cell and tubular dysfunction." (PMID 37533739, 2023).
COVID-19 (continued). "In patients with COVID-19 hospitalized in intensive care units, elevated serum levels of IL-1β, IL-7, IL10, IL-17, IL-2, IL-9, Th17, IFN-γ, GM-CSF, G-CSF, IL-8, TNF-α, MIP1B, MCP1, MIP1A, and IP10 were observed, suggesting that the relation between periodontitis and COVID-19 may be established." (PMID 34068221, 2021). "Second, certain pro-inflammatory cytokines (IL2, IL7, IL10, GCSF, IP10, MCP1, MIP1A, and TNF) were further increased in ICU patients compared with non-ICU patients, indicating that excessive acute inflammatory responses may lead to septic shock and death in COVID-19 patients." (PMID 32442210, 2020). "Remarkably, COVID-19 patients requiring intensive care unit (ICU) admission presented higher levels of CCL2, CXCL10, IL-2, IL-7, IL-10 and TNF-α than non-ICU patients, hinting the linkage between the cytokine storm and COVID-19 deterioration." (PMID 37251383, 2023). "We investigated the circulating levels of the G-CSF, GM-CSF, M-CSF, IL-3, IL-7, FLT3L and IL-2 growth factors and soluble receptor sIL2Ra in the surviving and non-surviving severe COVID-19 patients and healthy controls." (PMID 36142255, 2022). "On the other hand, some markers (i.e., IL-5, IL-7, IL-17A, CXCL8, and VEGF) were increased in critical COVID-19 patients only and not in macrophage activation syndrome." (PMID 35645351, 2022). "IL7, IL17RC, and IFNLR1 were upregulated in the early stages of COVID-19 while absent in later disease stages." (PMID 35983322, 2022). "One of the first studies to evaluate the serum cytokine storm in COVID-19 patients showed that several pro-inflammatory mediator levels, such as TNFα, IL-2, IL-7, IL-10, G-CSF, CXCL10, CCL2 and CCL3, were increased in ICU (n = 13) compared to non-ICU COVID-19 patients (n = 28)." (PMID 36941580, 2023). "Similarly, the plasma level of IL-2, IL-7, IL-10, and TNF-α increased in ICU COVID-19 patients compared to non-ICU COVID-19 patients." (PMID 38152668, 2023). "Moreover, in our cohort group, IL-1β, IL-7 and FGF-2 elevated in samples from patients with severe, but not with moderate COVID-19 compared to HDs." (PMID 36012146, 2022). "Furthermore, IL-2, IL-7, IL-10, G-CSF, IP-10, MIP-1α and1β, and TNF-α were higher in ICU COVID-19 patients than non-ICU patients." (PMID 35401519, 2022). "Similarly, in severe COVID-19 cases, ICU patients had higher plasma levels of IL-2, IL-7, IL-10, GSCF, MCP1, MIP1A, and TNFα compared to non-ICU patients." (PMID 32754890, 2020). "A previous study found that intensive care unit (ICU) patients with COVID-19 had higher plasma levels of interleukin (IL)-10, IL-2, IL-7, tumor necrosis factor (TNF)-α, IP-10, monocyte chemoattractant protein 1, Macrophage inflammatory protein 1A than those in non-ICU patients with COVID-19." (PMID 32727465, 2020).
lymphopenia (188 papers, 2005 to 2026). Reduction in the number of lymphocytes. "STING GOF T cells display signs of TCR and IL-7R engagement since the naive T cell stage, consistent with lymphopenia-associated signals provided by (auto)antigen and IL-7-mediated stimulation, respectively." (PMID 40804163, 2025). "In marked contrast, the IL-7–deficient patients displayed severe αβ T cell lymphopenia, whereas their γδ T cell counts and proportions were, surprisingly, similar to those in healthy individuals." (PMID 39352394, 2024). "In an RCT studying intramuscular recombinant human IL-7 (CYT107) in 27 patients with severe lymphopenia, CYT107 reversed the loss of CD4+ and CD8+ cells." (PMID 38807151, 2024). "IL-7 immunotherapy improved clinical symptoms, cleared the fungus, reversed lymphopenia, and reversed the profound loss of CD4+ and CD8+ T cells induced by sepsis." (PMID 38114466, 2023). "Our group has previously shown that plasma levels of IL-7 peak at the time of maximum lymphopenia and that increased IL-7 levels are associated with increased risk of grade II-IV aGVHD and reduced overall survival after HSCT." (PMID 38268913, 2023). "Exposure to ionizing radiation at specific dose and radiation qualities can lead to lymphopenia, and the genes for IL7, along with IL10 and Flt3 ligand, encode positive regulators of the lymphoid lineage after TBI." (PMID 30978983, 2019). "While IL-7 deficiency results in lymphopenia, overexpression of IL-7 can cause neoplasia in experimental models." (PMID 30373315, 2018). "We did not determine lymphocyte counts in the present study and cannot prove or refute lymphopenia as a possible cause for high IL-7 levels." (PMID 28582466, 2017). "Its serum level is mainly regulated through the up-take by lymphocytes, thus elevating IL-7 in conditions associated with lymphopenia." (PMID 27866242, 2017). "IL-7 increased proliferative capabilities and induced sustained increases of PBMC counts when administered in “clustered” doses; finally, IL-7 treatment prevented lymphopenia associated with IFN-α treatment while stimulating CD8+ CTLs against SIV." (PMID 26858716, 2016). "Lymphopenia-associated IL-7 overabundance contributes to the activation of naïve T cells, which undergo homeostatic or lymphopenia-induced proliferation (LIP) and convert into memory-like cells, which express high levels of CD44 and IFNγ." (PMID 27447484, 2016). "Lymphopenia, which is associated with increased circulating levels of IL-7 represents a typical condition in which autoreactive T cells can expand." (PMID 26983628, 2016). "IL-7 plays a critical role in homeostatic proliferation, survival and memory formation of naïve T-cells in lymphopenia, and its underlying molecular mechanism has also been well studied." (PMID 27158441, 2016). "Mice deficient in IL-7−/−, IL-7Rα−/−, γc−/− or Jak3−/− suffer from severe lymphopenia, particularly for T and NK cells." (PMID 25955647, 2015). "The levels of IL-7 required to upregulate the integrin, however, are associated with lymphopenia; an immunological state only generated late in HIV infection." (PMID 26105197, 2015). "Levels of total STAT1 (t-STAT1) were associated with the degree of lymphopenia and IL-7 serum levels in HIV-infected patients." (PMID 24603698, 2014). "Demonstration of IL-7 dependent modulation of IL-2 signaling also provides a rationale for the association between T cell lymphopenia and Treg enrichment." (PMID 25485946, 2014). "IL-7 deficiency in the RAG−/− background reduced IL-7 dependent lymphopenia-induced slow proliferation and survival of the transferred cells." (PMID 24603698, 2014). "Use of IL-7 has provided a future thymic rejuvenation strategy for the treatment of thymic atrophy-associated immune problems and lymphopenia-related diseases." (PMID 22448237, 2012).